LEP (leptin)
Diseases named in the same sentence as LEP in open-access papers (continued):
Sharing a sentence is not in itself a finding about the gene and the disease.
depression (continued). "The impact of chronic unpredictable stress (CUS), a paradigm that induces depression-related behavioral deficits in adult mice, and leptin treatment on social motivation were examined." (PMID 36138127, 2022). "In contrast, insulin and leptin resistance affect the normal function of brain tissue, which can lead to depression." (PMID 36387921, 2022). "In humans, leptin levels were found to correlate negatively with the severity of depression symptoms, Multiple lines of evidence suggest that leptin targets hippocampal neurons to regulate depression-related behaviors." (PMID 33106599, 2021). "Some studies indicate that patients with major depression have low leptin levels in the plasma and cerebrospinal fluid." (PMID 33667284, 2021). "Second, deletion of LepRb in the dentate gyrus results in depression-like behaviors and attenuates leptin’s antidepressant-like effects." (PMID 33106599, 2021). "An earlier meta-analysis illustrated a lower peripheral level of adiponectin in depressed patients compared with that in controls and suggested that males who have lower adiponectin and leptin levels have an increased likelihood of developing major depression." (PMID 33667284, 2021). "We and others have shown that circulating leptin levels are reduced in chronic stress animal models of depression, whereas systemic and intracerebroventricular injections of leptin produce antidepressant-like behavioral effects." (PMID 33106599, 2021). "A previous study found that plasma leptin levels were negatively correlated with PANSS depression factor scores (r = −0.255, Bonferroni corrected P = 0.028)." (PMID 34566714, 2021). "We also explored the possible associations among some of the essential blood and saliva components (cytokines, insulin, leptin, cortisol, and vitamin D) with measures of depression, social anxiety, and executive functions." (PMID 31973090, 2020). "Modifications of leptin metabolism and its gene expression, as well as its receptor, have been reported among patients with mental health disorders, including depression, independently of drug treatment." (PMID 33066277, 2020). "In particular, leptin reduces symptoms of depression and has an anxiolytic effect affecting the HPA, and stimulating brain-derived neurotrophic factor (BDNF) production and function." (PMID 33066277, 2020). "We also explored the associations among blood and saliva biomarkers (pro-inflammatory cytokines, vitamin D, insulin, leptin, and cortisol) with measures of executive functions depression, and social anxiety." (PMID 31973090, 2020). "Reduction in body fat by means of dietary restriction provoked not only a reduction in leptin levels but in parallel also led to a reduction in depression scores." (PMID 32408603, 2020). "In the results of their research, the ratio of pre-treatment pBDNF to leptin was significantly lower in patients with major depressive disorder compared to healthy controls." (PMID 32012942, 2020). "Several studies showed a particular interest in the relationship between leptin and depressive disorders, but with discordant conclusions." (PMID 32033608, 2020). "In the present study, we are showing the antidepressant-like effects of leptin in LPS-induced inflammatory model of depression through two established behavioral paradigms, namely forced swimming and sucrose preference test." (PMID 30949073, 2019). "Leptin's antidepressant-like effect was already demonstrated in stress models of depression, such as chronic unpredictable stress and chronic social defeat." (PMID 30949073, 2019). "The coexistence of increased circulating leptin and depression has been previously demonstrated, though in studies with small sample sizes and clinical heterogeneity." (PMID 31832026, 2019). "Our results indicate that leptin has antidepressant-like effects in an inflammatory model of depression with the contribution, at least partial, of dopamine receptors." (PMID 30949073, 2019).
depression (continued). "In many pharmacological studies on rodent models with depression-like behavior, it has been reported that leptin is regulated by leptin receptor activation in specific limbic regions, such as the hippocampus, and leptin has an antidepressant-like effect." (PMID 31231496, 2019). "In this article, we discussed the effects of adipocyte-derived hormone leptin in depression, AD, PD and its possible modulatory role." (PMID 31130833, 2019). "Schmid and collegues showed that leptin concentrations increased after 4 weeks of treatment depressive disorder patients with mirtazapine." (PMID 31231496, 2019). "Leptin plays a vital role in neuroplasticity, especially in depression-related regions of the brain." (PMID 30367065, 2018). "In any case, positive correlations between the severity of depression and leptin levels were observed." (PMID 30367065, 2018). "Studies in mice with genetic deletions of the leptin gene and the LepRb gene further confirmed the critical role of leptin in depression." (PMID 30367065, 2018). "Serum leptin levels in patients with moderate to severe depression were higher than those with mild or minimal depression." (PMID 30367065, 2018). "As with leptin, a body of work now supports the role of ghrelin in regulating mood, with close links to depression." (PMID 30405455, 2018). "In this review, we present the available evidence, and try to illuminate the potential cellular and molecular mechanisms of leptin’s antidepressant actions and its potential therapeutic capacity in the treatment of depression." (PMID 30367065, 2018). "Several studies have examined stress-treated rodents or genetically modified rodents as depression models to investigate the link between leptin and depression." (PMID 30367065, 2018). "The impact of probiotic treatment on leptin levels within the context of depression has recently been evaluated." (PMID 30405455, 2018). "A large longitudinal study demonstrated that serum leptin concentrations predicted the later development of major depression." (PMID 29176959, 2017). "The aim of the present study was to investigate the serum and tissue leptin-LepRb levels in GC patients with depression and to examine the relationship between leptin-LepRb and clinical factors in these patients." (PMID 28316984, 2017). "Esel group reported a positive correlation between leptin levels and depression symptoms in women only." (PMID 29176959, 2017). "The leptin and LepRb levels were significantly higher in patients who diagnosed GC accompanied with depression (7.9 ng/mL and 5.5 ng/mL, resp)." (PMID 28316984, 2017). "Collectively, these findings suggest a critical role of leptin-LepRb in depression and antidepressant therapy." (PMID 28316984, 2017). "Together, our findings suggest that leptin-LepRb plays an important role in the pathogenesis and depression in GC." (PMID 28316984, 2017). "Patients suffering from moderate to severe depression had higher levels of leptin than those suffering from mild depression." (PMID 27739518, 2016). "During the first treatment phase leptin levels were significantly positively related to the subjective ratings of depression, anxiety, and stress in HSS patients." (PMID 28030575, 2016). "The effects of HFD and CUMS on depression-like and anxiety-like behavior, leptin/LepRb signaling of the rats and their interaction impact were investigated." (PMID 27739518, 2016). "For example, the RR for CHD associated with leptin is relatively low, thus the connection line between depression and leptin is thin." (PMID 26231223, 2015). "Recent studies also suggest an antidepressant role for leptin as exposure of rodents to certain stress paradigms that model human depression results in a significant reduction in circulating leptin levels." (PMID 26464986, 2015).
depression (continued). "Overall it appears that leptin plays important roles in 1) the regulation of nutritional intake and energy balance, 2) the physiology of depression and anxiety, and 3) the orchestration of fetal nutritional intake and growth." (PMID 26303856, 2015). "The participation of leptin in depression was described in depressive patients and depressive animal models." (PMID 24906408, 2014). "In animal models of depression, administration of leptin has been shown to improve depressive behaviors and exert antidepressant-like effects." (PMID 25079305, 2014). "Only two studies, to our knowledge, have investigated the relationship between circulating leptin levels and depression in the general population: one in women only and another in elderly men and women." (PMID 25079305, 2014). "Longitudinal studies with large sample size, assessments of serum leptin and ghrelin at multiple times point, and follow-up assessments for clinical depression are needed to confirm the present findings." (PMID 25079305, 2014). "Patients with depression showed higher serum leptin levels at 3 month after stroke (32.2 [IQR, 20.8–57.7] v." (PMID 25061971, 2014). "Genetic deletion of LepRb in the hippocampus results in a depression-like phenotype, which is reduced by leptin administration to the hippocampus thereby showing an antidepressant effects." (PMID 25225489, 2014). "Hyperactivity of the hypothalamic-pituitary-adrenal (HPA) axis is a common feature of depression and accumulating evidence suggests that leptin reduces HPA activity." (PMID 25079305, 2014). "In the last years, the scientific interest for leptin has also been extended to psychiatric disorders, such as anxiety and depression." (PMID 25386150, 2014). "Our findings linking depression with higher level of leptin and lower levels of ghrelin seems reasonable given that leptin treatment improves monoamine neurotransmission and lessens HPA axis, whereas ghrelin has opposite effects." (PMID 25079305, 2014). "In an Australian study, women with a lifetime history of depression had elevated levels of leptin, and leptin levels predicted the subsequent development of de novo major depressive disorder over five years of follow-up, independently of BMI." (PMID 25079305, 2014). "On the other hand, there are reports showing increased plasma leptin levels in depression, gender specific increased leptin levels in women with depressive disorder, as well as no changes of leptin by antidepressant treatment." (PMID 25225489, 2014). "Whereas, some authors have found higher leptin levels in patients with depression, others have reported lower leptin levels." (PMID 25061971, 2014). "Several studies find that individuals with major depressive disorder (MDD) have lower plasma leptin levels compared to healthy controls with similar BMI." (PMID 24109426, 2013). "In a related study, we reported that 24-hour plasma leptin levels were about 30% higher in a subset of 23 women with depression compared to 23 BMI -matched controls." (PMID 22235252, 2012). "Elevated ACTH levels were demonstrated in women with atypical features of depression, whereas higher mean 24-hour leptin levels were observed in the melancholic subgroup." (PMID 22235252, 2012). "Future studies should determine if subjects with depression develop a resistance to the antidepressant effects of leptin when gaining weight." (PMID 22235252, 2012). "Clinically, leptin is strongly associated with atypical depression rather than melancholic depression." (PMID 41375608, 2025). "Although numerous epidemiological studies indicate elevated FetA levels in obese individuals and a positive correlation between FetA concentration and BMI, visceral adipose tissue (VAT), and leptin levels, the number of studies analyzing the relationship between FetA and depression remains limited." (PMID 40507778, 2025). "However, more research is needed to decipher the exact mechanism through which leptin intervenes in depression’s pathophysiology." (PMID 41375608, 2025).
depression (continued). "Leptin, a key anorexigenic hormone, has also been involved in depression and anxiety." (PMID 40565847, 2025). "Moreover, recent studies showed that the increased leptin plasma levels appear to represent an indirect mediator of clinical depression status and “somatic anxiety” symptoms in depressive individuals." (PMID 40565847, 2025). "This further supports the leptin resistance state that exists in depression." (PMID 41375608, 2025). "Therefore, future studies should stratify analyses by depressive subtype, sex, and metabolic profile to clarify the role of leptin in the pathogenesis of depression." (PMID 40507778, 2025). "However, contrasting findings have been reported in reproductive-aged women, where patients with depression and anxiety displayed lower leptin levels compared to healthy controls." (PMID 40565847, 2025). "Third, we did not measure other circulating peptides, such as leptin, which has been linked to depression or LEAP-2, an antagonist of ghrelin which can influence the activity of ghrelin." (PMID 39905823, 2025). "In summary, meta-analytic data underscore the heterogeneity of leptin findings in depression." (PMID 40507778, 2025). "Our findings about the increased circulating levels of both leptin and resistin in pregnant women with anxiety and depression posit that these two important adipocytokines (released from adipocytes or the brain) dysregulate the HPA axis bioactivity, at distinct levels, leading to hypercortisolemia." (PMID 40565847, 2025). "First, six infusions of ketamine associated with increased the levels of leptin and OPG, and decreased the levels of OC, OPN, SOST, PTH and FGF23 in patients with depression, which occurred immediately the day after the last infusion (Day 13) and lasted for 2-week post-infusion (Day 26)." (PMID 38287453, 2024). "However, further investigation is warranted to better understand the complex interplay between vitamin D, depression, and leptin levels in different populations and under varying conditions." (PMID 40226697, 2024). "High fructose consumption may also contribute to depression by altering the levels of inflammatory cytokines or certain hormones, such as leptin and ghrelin, which regulate appetite and mood." (PMID 38271962, 2024). "In addition, interactions between changes in depression symptoms and changes in different biomarkers such as leptin, adiponectin, HDL, and miR192-5p were observed." (PMID 38892481, 2024). "Therefore, within the sub-project of the SPeED study, circulating leptin levels of patients with depression were compared with healthy controls before and after an acute exercise bout and long-term exercise intervention." (PMID 38098007, 2023). "There are data on the relationship between depression and leptin status." (PMID 36674935, 2023). "The study hypothesized that elevated leptin levels at night increase CRH secretion, a hormone associated with the progression of depression." (PMID 37399205, 2023). "As proposed in several basic studies, leptin has antidepressant effects and might be a potential therapeutic target for depression." (PMID 38098007, 2023). "A meta-analysis also supports the inconsistent involvement of leptin with major depression." (PMID 37399205, 2023). "Though many research has been conducted to determine the relationship between leptin and depression, a concrete association was not established yet." (PMID 37399205, 2023). "Animal studies have shown that leptin can have an antidepressant-like effect, and some clinical trials have suggested that leptin administration may improve symptoms of depression in humans." (PMID 37238961, 2023). "Many clinical studies have looked into the connection between leptin and depression." (PMID 37399205, 2023). "Also, plasma leptin has been negatively correlated, as in our case, with symptoms of anxiety and depression." (PMID 37836393, 2023).
depression (continued). "Moreover, to the best of our knowledge, this investigation is the first attempt in Bangladesh to find out the involvement of serum leptin and EGF levels with depression and to find out their association with the severity of depression." (PMID 37399205, 2023). "Depression may be characterized by elevated pro-inflammatory signaling via leptin concentrations through alternate inflammatory pathways distinct to CRP." (PMID 37443383, 2023). "Inflammation can reduce leptin signals to the central nervous system that influence depression and leptin may modulate HPA function." (PMID 35911226, 2022). "In summary, leptin has been confirmed as the target of PF in ameliorating the symptoms in PI-IBS rats, such as excessive fibrotic remodeling in the submucosa and depression- and anxiety-like behaviors via the inhibited activation of the leptin/LepRb downstream pathway—the PI3K/AKT pathway." (PMID 36225193, 2022). "Furthermore, given the complexity of the symptoms of schizophrenia and previous results, which shown that declined leptin occurred in patients with severe suicidal behavior or depression, we listed and analyzed the depressive factors solely." (PMID 35197874, 2022). "In addition, Mounting evidence reveals that obesity-related metabolic dysfunction, including inflammation, insulin and leptin resistance, and hypertension, have emerged as key risks to depression." (PMID 35692399, 2022). "Lastly, although previous literature has found some relationship between leptin and depression, we found no LEP or LEPR haplotype associations with MADRS scores." (PMID 34421692, 2021). "In rat models, CR but also leptin injections were shown to directly enhance neurogenesis and cell survival in the hippocampus, a well-established core region of structural and functional impairment in depression." (PMID 34834448, 2021). "Therefore, the present study specifically evaluates the mutual relationships between adiponectin and leptin and anxiety and depression in postmenopausal women." (PMID 33667284, 2021). "The initial enthusiasm regarding the possible utility of adiponectin and leptin as diagnostic depression biomarkers has not been justified." (PMID 33667284, 2021). "Interestingly, earlier and recent large-scale genomic studies found that the genetic overlap between BMI, CRP and leptin with depression is symptom specific; this overlap was only found in depressed patients with increased hypersomnia, weight and appetite." (PMID 34078486, 2021). "The improvement in depression correlated with normalization of pro-inflammatory biomarkers, including pro-inflammatory adipokines (leptin) or cytokine (IL-6), suggests a role for inflammatory pathways and intriguing links between PPARγ activation, depression, and inflammation." (PMID 32971941, 2020). "But importantly, whereas high leptin levels seem to predict depression ratings in females, they did not associate with male depression." (PMID 32408603, 2020). "We obtained plasma leptin levels and depressive symptom measures (Hamilton Depression Rating Scale (HAMD)) within 24 h of scanning and compared the regional homogeneity (ReHo), plasma leptin levels and HAMD total score and factor scores between patients and healthy controls." (PMID 32699219, 2020). "In our study, multiple stepwise regression analysis did not reveal a significant association between leptin and depression." (PMID 33023555, 2020). "Some other studies showed that leptin levels are increased in major depressive disorders, but only in patients experiencing atypical features, suggesting that leptin may be involved in a subset of patients with increased weight." (PMID 32033608, 2020). "Studies of the relationship between leptin and major depression are gradually increasing." (PMID 31354416, 2019). "The role of leptin in depression has been extensively investigated." (PMID 30949073, 2019).